ACE (angiotensin I converting enzyme)
Diseases named in the same sentence as ACE in open-access papers (continued):
Sharing a sentence is not in itself a finding about the gene and the disease.
disc degeneration (1 paper, 2025). "This study aims to elucidate the molecular mechanisms by which ACE regulates PSAP stability through glycosylation, investigate how PSAP‐GPR37 interaction mediates NP cells‐macrophages communication, and explore the therapeutic potential of targeting this pathway for disc degeneration treatment." (PMID 41085015, 2025).
disseminated candidiasis (1 paper, 2016). Systemic candidiasis occurs when Candida yeast enters the bloodstream and may spread (becoming disseminated candidiasis) to other organs, including the central nervous system, kidneys, liver, bones, muscles, joints, spleen, or eyes. "In addition, the efficacy of ACE inhibitors, known to increase the levels of bradykinin and are routinely used to treat patients with obstructive nephropathy, need further evaluation in pre-clinical animal models of disseminated candidiasis." (PMID 27814401, 2016).
E Coli infection (1 paper, 2022). "KEGG pathway analysis demonstrated the gene set was enriched in DNA replication, steroid biosynthesis, ACE-RAGE signaling, TNF signaling, and pathogenic E Coli infection." (PMID 36229484, 2022).
Ebola virus disease (1 paper, 2023). "This suggestion is consistent with the results of the field trials of ACE inhibitors and statins in human Ebola virus disease that have already demonstrated some success." (PMID 36851566, 2023).
erythroderma (1 paper, 2023). "Many medications can cause erythroderma, including antibiotics, antiepileptics, angiotensin-converting enzyme (ACE) inhibitors, and sulfonamides." (PMID 37766779, 2023).
femoral neck fracture (1 paper, 2021). Fractures of the short, constricted portion of the thigh bone between the femur head and the trochanters. "In comparison with those in the synovium from patients with femoral neck fracture, the expressions of AT1R, AT2R, and ACE in the interface membrane from patients with PPOL were up-regulated." (PMID 34248634, 2021).
Fibroadenoma (1 paper, 2006). A benign tumor of the breast characterized by the presence of stromal and epithelial elements. "In fibroadenoma too, epithelial cells, stained positively for ACE." (PMID 16755291, 2006).
G6PD deficiency (1 paper, 2013). An X-linked genetic condition caused by alterations in the gene G6PD that result in moderately to severely decreased activity levels of the enzyme glucose-6-phosphate dehydrogenase. "We have reported previously an association between ACE gene polymorphism and G6PD deficiency." (PMID 24289455, 2013).
gangrene (1 paper, 2025). Death of tissue, usually in considerable mass and generally associated with loss of vascular (nutritive) supply and followed by bacterial invasion and putrefaction. "Through a systematic analysis of 12 drugs and six key genes (IGF1, IL17A, ACE, FGF2, IL6 and TLR4), we have provided a new scientific perspective on gangrene prevention in diabetic patients." (PMID 40657379, 2025).
gingival overgrowth (1 paper, 2025). Excessive growth of the gingiva either by an increase in the size of the constituent cells (gingival hypertrophy) or by an increase in their number (gingival hyperplasia). "Discontinuation of amlodipine, followed by new drug therapy based on angiotensin II receptor antagonists (ACE inhibitors), proved effective in reducing inflammation associated with gingival overgrowth within approximately 20 weeks." (PMID 39941250, 2025).
Gitelman syndrome (1 paper, 2024). Gitelman syndrome (GS), also referred to as familial hypokalemia-hypomagnesemia, is characterized by hypokalemic metabolic alkalosis in combination with significant hypomagnesemia and low urinary calcium excretion. "The management of Gitelman Syndrome (GS) is predominantly aimed at alleviating symptoms and rectifying electrolyte imbalances through the supplementation of potassium and magnesium, alongside the employment of ACE inhibitors (ACEIs)/angiotensin receptor blockers (ARBs) and aldosterone antagonists." (PMID 39055258, 2024).
head and neck squamous cell carcinoma (1 paper, 2023). A squamous cell carcinoma that arises from any of the following anatomic sites: lip and oral cavity, nasal cavity, paranasal sinuses, pharynx, larynx, and salivary glands. "As a result of the small sample size in the GEO database and the lack of specific NPC samples in the TCGA database, we analyzed the mRNA expression levels of ACE in head and neck squamous cell carcinoma (HNSCC) from the TCGA database." (PMID 37371679, 2023).
heart cancer (1 paper, 2021). "We concluded that heart cancer patients could be affected by beta-adrenergic blockers, ACE inhibitors, QT-prolonging antiarrhythmic drugs, antibiotics, and antipsychotics." (PMID 34359782, 2021).
hematoma (1 paper, 2024). A hematoma is a collection of blood from a vascular structure into an extravascular space. "Once corrected for hematoma architecture, type of surgery, and use of antithrombotic medication, in a multivariate regression model, preoperative use of ACE inhibitors was associated with a twofold increase in the likelihood of hematoma recurrence." (PMID 39200732, 2024). "Once corrected for hematoma architecture, type of surgery, and the use of antithrombotic medication, preoperative use of ACE inhibitors was associated with a twofold increase in the likelihood of developing hematoma recurrence." (PMID 39200732, 2024). "This study assesses the hypothesis that ACE inhibitors may affect recurrence rates by altering hematoma membrane formation." (PMID 39200732, 2024). "The primary goal of this study was to assess whether prior intake of ACE inhibitors affected the hematoma’s architecture and formation of membranes on CT imaging." (PMID 39200732, 2024). "In the current study, we hypothesized that ACE inhibitors might affect the formation of hematoma membranes." (PMID 39200732, 2024). "Assessment of the levels of angiogenetic factors, such as vascular endothelial or placenta growth factor in both serum and hematoma, could shed light on the pathophysiological basis by which cSDH formation and healing may be altered by ACE inhibitor use." (PMID 39200732, 2024). "The distribution of architectural hematoma subtypes was not affected by prior use of ACE inhibitors." (PMID 39200732, 2024). "In this pooled cohort of 2.411 patients, 96 (20.7%) out of 464 patients on ACE inhibitors developed recurrent hematoma vs. 313 (16.1%) patients out of a total of 1.947 without prior ACE inhibitor treatment (OR 1.362, 95% CI 1.055 to 1.758; p = 0.018)." (PMID 39200732, 2024).
Hepatosplenomegaly (1 paper, 2025). Simultaneous enlargement of the liver and spleen. "At the age of one year and four months, imiglucerase dose was increased from 60 to 120 U/kg/dose due to re-elevated ACE, AST, and ALT levels and residual hepatosplenomegaly." (PMID 40236727, 2025).
hip fracture (1 paper, 2015). Traumatic or pathological injury to the hip in which the continuity of either the femoral head, femoral neck, intertrochanteric or subtrochanteric regions is broken. "A population-based case–control study in Denmark reported a 14 % reduction in hip fracture risk (adjusted OR 0.86, 95 % CI 0.80-0.92) in users of ACE inhibitor compared with nonusers; the crude OR was not significant." (PMID 26626043, 2015).
hypercortisolism (1 paper, 2023). "As a generalized up-regulation of the RAAS is observed in patients with hypercortisolism, angiotensin-converting enzyme inhibitors (ACE-Is) or angiotensin receptor blockers (ARBs) should be considered the first-line approach to lowering BP levels in MACS patients." (PMID 38137336, 2023).
hypersensitivity vasculitis (1 paper, 2026). A small vessel vasculitis affecting the skin and/or internal organs. "This case highlights that ACE inhibitor-associated hypersensitivity vasculitis may present with small bowel edema and imaging findings overlapping with intestinal angioedema." (PMID 41853412, 2026). "Angiotensin-converting enzyme (ACE) inhibitor-associated hypersensitivity vasculitis with gastrointestinal involvement is an uncommon but important drug-related cause of acute abdominal pain and may mimic an acute surgical abdomen." (PMID 41853412, 2026).
hypoparathyroidism (1 paper, 2024). Hypoparathyroidism is an endocrine disorder in which the parathyroid glands in the neck do not produce enough parathyroid hormone (PTH). "As expected, at the last visit, patients in group H had a significantly greater use of drugs related to the treatment of hypoparathyroidism, i.e., calcium, calcitriol, and thiazide diuretics, as well as a slight but significant lower use of angiotensin-converting enzyme (ACE) inhibitors." (PMID 38481445, 2024). "As expected, at last visit, the use of drugs related to hypoparathyroidism was significantly higher in group H. However, the use of remaining drugs at last visit was similar in both groups, with the exception of a higher proportion of ACE inhibitor users in group NH (group (27.1 vs. 20.8%; P=0.031)." (PMID 38481445, 2024).
idiopathic membranous nephropathy (1 paper, 2010). "We have studied the effects of add-on spironolactone treatment (100 mg/day) in 11 patients with idiopathic membranous nephropathy (IMN) and >3 gm proteinuria/day despite angiotensin converting enzyme (ACE) inhibitor therapy titrated to a systolic/diastolic blood pressure <120/80 mmHg." (PMID 27713239, 2010).
impulsive control disorder (1 paper, 2022). "ACE gene polymorphisms have been demonstrated to increase the risk for PD, and the rs4646994 polymorphism of ACE has been recently associated with impulsive control disorder in PD patients." (PMID 35741861, 2022).
insulinoma (1 paper, 2013). "In detail, we proved the following constituents of RAS to be present in the BRIN-BD11 rat insulinoma cell line: ACE, AT1bR, AT2R, ACE2, NEP, Mas, APA, APN and IRAP, but not AT1aR." (PMID 23942780, 2013).
invasive ductal carcinoma (1 paper, 2006). "In invasive ductal carcinoma grade III, ACE was expressed in the epithelial cells but apparently less uniformly strong than in normal tissue." (PMID 16755291, 2006).
keratinocyte carcinoma (1 paper, 2016). A skin cancer arising from the keratin-producing cells of the epidermis. "A similar finding was observed in a cohort study performed among a high-risk group of veterans using ACE inhibitors, showing a lower incidence of keratinocyte cancer when compared to nonusers." (PMID 27992423, 2016).
kidney transplant (1 paper, 2024). A surgical procedure in which one or both kidneys from a donor are implanted into a recipient. "Therefore, it would be appropriate to investigate the impact of ACE polymorphisms on the risk of kidney transplant rejection." (PMID 38398308, 2024).
latent syphilis (1 paper, 2016). A stage of syphilis characterized by the serologic evidence of infection by Treponema pallidum without evidence of accompanying signs or symptoms related to the disease. "Our study disclosed that increase in serum lysozyme levels is more significant than increase in serum ACE levels for patients with infectious uveitis such as presumed latent TB and presumed latent syphilis." (PMID 26879979, 2016). "The mean (SD) differences of serum ACE levels between control group and AS, BD, presumed latent TB, presumed latent syphilis were −8.110 (4.288), −10.232 (4.285), −11.250 (4.528), and −9.195 (6.520) respectively." (PMID 26879979, 2016).
macular edema (1 paper, 2020). "Also, the RAS drug block at the level of angiotensin-converting enzyme (ACE) or angiotensin receptors decreases intraretinal angiogenesis and decreases vascular leakage, which is the cause of macular edema." (PMID 33062311, 2020).
McArdle disease (1 paper, 2014). "ACE polymorphism also modulates the clinical presentation of McArdle disease (the D/-, DD genotypes being associated to a more severe phenotype); based on these observations, a clinical trial with ACE-inhibitors was started." (PMID 25103075, 2014).
medullary thyroid carcinoma (1 paper, 2023). "Even though improved diagnostic efficacy during single NEP inhibition has been recently confirmed for a biodegradable radiolabeled gastrin analog in medullary thyroid carcinoma patients, the clinical translation of this concept in the case of NT radioligands would require dual ACE/NEP inhibition." (PMID 37958525, 2023).
mesothelioma (1 paper, 2024). A usually malignant and aggressive neoplasm of the mesothelium which is often associated with exposure to asbestos. "ACE expression is protective against kidney renal clear cell carcinoma (KIRC) and mesothelioma (MESO) but may present risks in uterine carcinosarcoma (UCS)." (PMID 39635438, 2024).
methamphetamine dependence (1 paper, 2025). A drug dependence that is a psychological dependency on the regular use of methamphetamine. "Future research should investigate the potential of agents with anti‐inflammatory or endothelial‐protective properties—such as statins, ACE inhibitors or novel immunomodulatory drugs—as adjunct treatments in methamphetamine dependence." (PMID 41368944, 2025).
mitral annular calcification (1 paper, 2016). "Davutoglu and Nacak reported that the I allele of the rs4340 polymorphism within the ACE gene (encoding angiotensin-converting enzyme) correlated with a higher risk of mitral annular calcification." (PMID 27589735, 2016).
Mycoplasma pneumoniae pneumonia (1 paper, 2023). Interstitial pneumonia caused by extensive infection of the lungs (lung) and bronchi, particularly the lower lobes of the lungs, by mycoplasma pneumoniae in humans. "In another study the combination of eNOS 894T and ACE D variants was found to contribute to the genetic susceptibility to Mycoplasma pneumoniae pneumonia." (PMID 36819141, 2023).
nephronophthisis (1 paper, 2023). Progressive tubulointerstitial injury, inherited in an autosomal recessive pattern, caused by mutations in genes involved in ciliary function, which may result in an end stage renal failure. "This technique has been used in diverse mice models such as healthy mice, nephrectomised mice, and animals with nephronophthisis; C57BL/6, Balb/c, SV129, NMRI mice lean and obese C57BL/6J mice and animals lacking renal angiotensin-converting enzyme (ACE)." (PMID 37552296, 2023).
non-melanoma skin carcinoma (1 paper, 2022). "27.15% of the insured received at least one prescription of ACE inhibitors within 5 years prior to the diagnosis of non-melanoma skin cancer or an operation in the periocular region." (PMID 35175408, 2022).
opioid use disorder (1 paper, 2018). A substance-related disorder that involves the recurring use of opioids despite negative consequences. "OUD - opioid use disorder, SSRI - selective serotonin reuptake inhibitors, ACE - angiotensin-converting enzyme." (PMID 30018867, 2018).
Oral ulcer (1 paper, 2024). Erosion of the mucous mebrane of the mouth with local excavation of the surface, resulting from the sloughing of inflammatory necrotic tissue. "In some cases, oral ulcers may also be induced by medications, including nonsteroidal anti-inflammatory drugs (NSAIDs), beta-blockers, and angiotensin-converting enzyme (ACE) inhibitors." (PMID 38975411, 2024).
ovarian diseases (1 paper, 2025). "As shown in our results and previous studies, PCOS is frequently associated with abnormal RAS activity in non-iatrogenic ovarian diseases, particularly in terms of total renin concentrations, ACE activity, and AngII levels." (PMID 40425574, 2025).
ovarian tumor (1 paper, 2024). "Authors also detected angiotensin converting enzyme (ACE) in ovarian tumor stroma." (PMID 38439058, 2024).
pancreatic adenocarcinoma (1 paper, 2021). "Similarly, ACE, ACE2, and AGTR1 were significant prognostic factors for overall survival (OS) in KIRC and LGG, whereas ACE, AGT, and AGTR1 were significant prognostic factors for OS in pancreatic adenocarcinoma (PAAD)." (PMID 34671200, 2021).
pancreatic exocrine insufficiency (1 paper, 2021). "Interestingly, patients taking angiotensin-converting enzyme (ACE) inhibitors experience pancreatic exocrine insufficiency less frequently, presumably due to the potential anti-fibrotic effects of the ACE inhibitors." (PMID 34945075, 2021).
panic disorder (1 paper, 2022). An anxiety disorder characterized by multiple unexpected panic attacks with persistent concern of recurring attacks. "The I/D polymorphism of the angiotensin I-converting enzyme (ACE) gene is more common in male patients with panic disorder, and primary hyperaldosteronism is associated with GAD." (PMID 36555831, 2022).
parasitemia (1 paper, 2024). "In the same mouse model, a discrete but significant reduction in parasitemia was observed when infected mice were treated with captopril, an ACE inhibitor used to reduce the formation of Ang II27." (PMID 38409185, 2024).
pheochromocytoma-paraganglioma (1 paper, 2021). A rare neuroendocrine tumor arising from chromaffin cells of the adrenal medulla (pheochromocytoma) or from sympathetic and parasympathetic ganglia (paraganglioma). "In some subjects with inherited pheochromocytoma/paraganglioma (PPG) syndromes, hypoxia-inducible factor 1 alpha (HIF1α) stabilization/activation could lead to an increase in angiotensin converting enzymes (ACE)." (PMID 34684070, 2021).
pityriasis rosea (1 paper, 2025). A mild, self-limited skin disorder that is most commonly seen in children and young adults. "According to Wilkin’s hypothesis, ACE inhibitors might raise plasma and tissue levels of kinins, which have pro-inflammatory effects linked to various cutaneous adverse reactions, including pityriasis rosea-like eruptions." (PMID 39804489, 2025).
plaque psoriasis (1 paper, 2024). "The sudden flare-up of plaque psoriasis in a patient with a stable history following the initiation of an ACE inhibitor highlights the importance of considering patient history when prescribing these medications." (PMID 39364528, 2024).
Polydipsia (1 paper, 2019). Excessive thirst manifested by excessive fluid intake. "The primary polydipsia associated with the inhibition of ACE declined inner medullary aquaporin (AQP) 2, without significant change AQP3 and AQP4 expression." (PMID 31116771, 2019).
Postural instability (1 paper, 2025). A tendency to fall or the inability to keep oneself from falling; imbalance. "Many of these drugs also have direct ototoxic and vestibular effects, such as dizziness and postural instability, as documented for loop diuretics such as furosemide and for ACE inhibitors like enalapril." (PMID 41148760, 2025).
Primary hypothyroidism (1 paper, 2025). A type of hypothyroidism that results from a defect in the thyroid gland. "Interestingly, a previous study found that the ACE index and Chao 1 index in primary hypothyroidism patients elevated compared with normal controls." (PMID 40052844, 2025).
prostate (1 paper, 2020). "Considering that ACE2 antagonizes the effects of ACE, it is probable that downregulation of ACE2 expression as in SARS-CoV-2 infection, which implies elevated ACE activity, may potentiate prostate carcinogenesis." (PMID 32974166, 2020).
pulmonary regurgitation (1 paper, 2025). "The APPROPRIATE study, a single-center, double-blind, placebo-controlled study, evaluated the effects of ramipril, an angiotensin-converting enzyme (ACE) inhibitor, in 64 stable patients with rTOF and moderate or severe pulmonary regurgitation." (PMID 41351752, 2025).
renal tubular disease (1 paper, 2022). "Unlikely, a missense variant in ACE protein (Q1069R) was reported to be associated with renal tubular disease resulting in premature death caused by improper localization of ACE and loss of its function." (PMID 36056420, 2022).
renal tumor (1 paper, 2017). "For example, ACE, ACE2 and NEP/CD10 activity was markedly decreased in renal tumors with respect to normal tissues." (PMID 28809959, 2017).
retinal diseases (1 paper, 2017). "In addition to being potent classifiers, IL-21, IL-10, and ACE may have distinct biological functions in these retinal diseases." (PMID 28128370, 2017).